FKBP5 (FKBP prolyl isomerase 5)
Diseases named in the same sentence as FKBP5 in open-access papers (continued):
Sharing a sentence is not in itself a finding about the gene and the disease.
Tinnitus (1 paper, 2026). Tinnitus is an auditory perception that can be described as the experience of sound, in the ear or in the head, in the absence of external acoustic stimulation. "The glucocorticoid receptor NR3C1 and its interaction with FKBP5, a glucocorticoid receptor-induced co-chaperone, appear to be of particular importance for the emotional aspects of tinnitus." (PMID 41751990, 2026).
psychiatric disorder (84 papers, 2011 to 2026). A disorder characterized by behavioral and/or psychological abnormalities, often accompanied by physical symptoms. "For example, methylation changes at FKBP5 loci have been linked to stress-related psychiatric disorders, metabolic diseases, and immune-inflammatory conditions." (PMID 40017583, 2025). "It functions as a regulator of glucocorticoid (GC) signaling, and the FKBP5 gene is associated with many stress-related psychiatric disorders." (PMID 40017583, 2025). "Dysregulation of FKBP5 expression has been linked to stress-related psychiatric disorders, inflammation, and metabolic diseases." (PMID 40017583, 2025). "To contribute to the large body of evidence linking FKBP5 to several psychiatric disorders (for a review see7), we tested for associations between the CATT haplotypes of FKBP5, different types of childhood trauma, and different types of dissociative phenomena." (PMID 40764371, 2025). "Dysregulation of FKBP5 expression is associated with psychiatric disorders and other stress-related phenotypes in humans and laboratory models." (PMID 39022893, 2024). "We investigated the association between the four psychiatric disorder-associated SNPs in the FKBP5 gene and OSA-related quantitative sleep parameters, including respiratory events, oxygen traits and objective sleep-related variables." (PMID 37274192, 2023). "A large body of research has found that single nucleotide polymorphisms (SNPs) in FKBP5 are associated with a number of psychiatric disorders, including mood and anxiety disorders, PTSD, psychosis, and substance abuse disorders." (PMID 37274192, 2023). "FK506 binding protein 51 kDa (FKBP51), encoded by the FKBP5 locus on chromosome 6p21.31, is a gene with strong evidence that it cross-diagnostically contributes to the pathogenesis of psychiatric disorders in a subset of patients." (PMID 36729133, 2023). "In this review, we attempted to discuss the effects of the FKBP5 gene, its mutations on different psychiatric diseases, and drugs affecting the FKBP5 gene." (PMID 37398599, 2023). "The extensive evidence of heightened FKBP5/1 expression as a risk factor for psychiatric disorders has spurred the development of small-molecule FKBP5 antagonists as novel therapeutics." (PMID 36729133, 2023). "Carriers of the FKBP5 risk haplotype are at an increased risk of developing a psychiatric disorder, but only if exposed to early life adversity." (PMID 36729133, 2023). "The top site in the continuous response analysis was located in FKBP5, a gene which is known to be an important endogenous regulator of the stress hormone system possibly linked to stress-related psychiatric disorders such as depression." (PMID 34091594, 2021). "Candidate studies have identified a link between FK506-binding protein 5 (FKBP5) allelic variants and psychiatric disorders." (PMID 30963102, 2019). "The associations of oral contraceptives with higher FKBP5 mRNA and altered phospholipid levels were modified by rs1360780, a genetic variance implicated in psychiatric diseases." (PMID 29074884, 2017). "Genetic variation of FKBP5 has additionally been shown to interact with early life stress (ELS) to epigenetically program GR-induced transcription of FKBP5, leading to increased risk for the development of stress-related psychiatric disorders." (PMID 25352794, 2014). "FKBP5 has been implicated in psychiatric disorders because of its role encoding a co-chaperone protein for the glucocorticoid receptor." (PMID 24885933, 2014). "Notably, FKBP51, encoded by the FKBP5 gene, is more susceptible to external influences and has been linked to the onset of psychiatric disorders, emerging as a key focus of current research." (PMID 40182637, 2025). "They hypothesised that increased FKBP5 induction tightens the feedback loop and leads to GR resistance, leading to prolonged stress response and increased risk for stress-related psychiatric disorders." (PMID 38338761, 2024).
psychiatric disorder (continued). "It is also possible that microglia-associated FKBP5 expression may be reflective of increased microglia numbers, which is suggested to occur in psychiatric disorders." (PMID 36729133, 2023). "The association between FKBP5 SNPs and different psychiatric diseases." (PMID 37398599, 2023). "However, genetic variations of Fkbp5 that results in excessive FKBP51 expression has been linked to the pathogenesis of psychiatric disorders due to the increase of vulnerability to stress-related anxiety and depression." (PMID 35705957, 2022). "A more far-reaching aim was to demonstrate that the humanised Fkpb5 × ELA mouse model can be used to further investigate the influence of the human FKBP5 gene variants on the risk and resilience to stress and to further elucidate their contribution to psychiatric disorders." (PMID 35449298, 2022). "Considering the central role of stressor exposure for the association of FKBP5 and psychiatric disorders, our findings point in the direction that, as a chronic disease, CHD in itself might act as stressor." (PMID 32860562, 2020). "We then examined methylation in a shortlist of genes that were previously associated with early life stress and psychiatric disorders as well as placental functioning: Ank3, Avp, Avpr1a, Avpr1b, Bdnf, Cacna1c, Cyp11b1, Cyp11b2, Fkbp5, Hsd11b1, Igf2, Morc1, Nr3c1, Oxt, Oxtr, Pclo, Slc6a4." (PMID 30655507, 2019). "Previous research has focused on FKBP5 and its association with various psychiatric disorders." (PMID 27527158, 2016). "A functional polymorphism in FKBP5 intron 2 alters mRNA and protein induction following GR activation, such that the allele associated with stronger FKBP5 mRNA induction associates with GR resistance and an increased risk of a number of psychiatric disorders following childhood trauma." (PMID 28018293, 2016). "Given the necessity of exploring the molecular underpinnings of GxE interplay in psychiatric disorders, the recently engineered mice could present a powerful tool for studying the effects of human FKBP5 polymorphism-related glucocorticoid response in disease-relevant tissues." (PMID 38317011, 2024). "An enhanced risk for development of stress-associated psychiatric disorders in adulthood was shown to be associated with childhood trauma-dependent, allele-specific demethylation of the functional glucocorticoid response elements of FKBP5 gene playing an important role in regulation of the HPA axis." (PMID 29246185, 2017). "Fkbp5 is a glucocorticoid receptor binding protein that plays a strong role in psychiatric disorders and is induced by stress." (PMID 38887549, 2024). "FKBP5 acts as a co-chaperone of the glucocorticoid receptor activated in response to stress, with major implications in the pathology of several psychiatric disorders and the impact of stress on substance withdrawal, craving, and relapse." (PMID 38296993, 2024). "A significant discovery has been the association of decreased DNA methylation levels in intron 7 of FKBP5 among individuals with psychiatric disorders." (PMID 38786025, 2024). "There is a positive correlation between these changes in FKBP5 gene expression levels and mental disorders." (PMID 37398599, 2023). "We then examined the effects of age on FKBP5 gex in cases compared to controls (subjects > 14 years), to determine if having a psychiatric disorder alters the neurotypical increase in FKBP5 gex with age." (PMID 36729133, 2023). "FKBP5 expression in peripheral blood has been shown to serve as a potential biomarker in several psychiatric disorders." (PMID 33673722, 2021). "Epigenetic activation of the FKBP Prolyl Isomerase 5 (FKBP5) gene has been shown to be associated with increased stress sensitivity and the risk of psychiatric disorders." (PMID 34071989, 2021). "The FKBP5 gene-environment interaction model has been shown to be related to various psychiatric disorders." (PMID 33673722, 2021).
psychiatric disorder (continued). "Epigenetic dysregulation of NR3C1 and FKBP5 have repeatedly been observed in psychiatric disorders following early life stress." (PMID 31040859, 2019). "CpGs previously associated with stress and psychiatric disorders, including CpGs in NR3C1 and FKBP5, replicates poorly across studies and have so far failed to translate into reliable clinical tests." (PMID 31040859, 2019). "Another example is the allele-specific demethylation of long-range enhancers of the FKBP5 (FK506 binding protein 5) gene, which increases the susceptibility of developing stress-related psychiatric disorders in adulthood." (PMID 30687383, 2018). "FKBP5 encodes FK506-binding protein 5, a glucocorticoid receptor (GR)-binding protein implicated in various psychiatric disorders and alcohol withdrawal severity." (PMID 27527158, 2016). "Overall, variations in the FKBP5 gene and its methylation levels may lead to various mental illnesses and health issues." (PMID 40017583, 2025). "As most reported studies about FKBP5 on Pubmed are related to energy metabolism, cell proliferation and cancer, stress‐related diseases, and phenotypes, immune function, FKBP5 in clinical studies was focused on stress‐related psychiatric diseases." (PMID 41170704, 2025). "It was hypothesised that demethylation of FKBP5 caused by excessive cortisol exposure during early life stress leads to long-lasting HPA axis dysregulation, enhancing the risk for stress-related psychiatric disorders in adulthood." (PMID 38338761, 2024). "Similarly, previous studies have shown that FKBP5 expression levels are positively correlated with psychiatric disorders, and a higher expression of FKBP5 was correlated with behavioral and neuroendocrine parameters." (PMID 38600448, 2024). "Altered FKBP5 gene expression, regulated by DNA methylation, is hypothesised to disrupt the HPA feedback loop and enhance the risk for stress-related psychiatric disorders." (PMID 38338761, 2024). "FKBP5 could be an interesting therapeutic target for the prevention and treatment of stress-related psychiatric disorders." (PMID 38600448, 2024). "Previous gene × environment studies investigating the effects of the FKBP5 risk haplotype on the development of psychiatric disorders have reported a cross-diagnostic effect that is not specific to one disorder, but can raise risk to many psychopathologies." (PMID 36729133, 2023). "Despite the strong negative impact of psychiatric disorders on quality of life and productivity, the underlying processes linking FKBP5 genotypes, stress regulation and pathological transitions are not fully understood." (PMID 35449298, 2022). "Human and animal studies point to a strong correlation between FKBP5 gene variants and environmental factors (in particular, experience of stress early in life) in psychiatric disorders, thereby implying the participation of epigenetic mechanisms in the regulation of FKBP5 expression." (PMID 36430271, 2022). "Thus, both methodological differences and possible confounders such as psychiatric disorders and childhood adversity are important when assessing methylation patterns of the FKBP5 gene and the HPA axis function." (PMID 34635736, 2021). "Finally, we were not able to control for some additional factors that have been shown to be modulate the influence of FKBP5 gene variation on psychiatric disorders e.g. trauma, especially in childhood, or comorbidity with other psychiatric disorders." (PMID 32860562, 2020). "However, the results regarding a genetic main effect of FKBP5 on psychiatric disorders remain inconsistent." (PMID 32860562, 2020). "Although the precise mechanisms remain to be elucidated, it appears safe to assume that epigenetic modulation and polymorphisms of FKBP5 contribute to the neuroendocrine alterations of the HPA system, which have been identified as a hallmark feature of stress-related mental illness." (PMID 28393267, 2017).
psychiatric disorder (continued). "The naturally occurring Fkbp5-SNPs in laboratory rodents do not feature comparable functional effects as rs1360780 in humans, where the AT- vs. CG-allele is more strongly induced by glucocorticoids and linked to the aetiology of psychiatric disorders." (PMID 35449298, 2022). "In combination with early‐life adversity, demethylation of FKBP5 has been reported, which could lead to a higher expression of FKBP5 rendering the affected individual more prone to glucocorticoid resistance and psychiatric disorders." (PMID 33030232, 2021). "Numerous studies have associated abnormalities in the functioning of the hypothalamic–pituitary–adrenal (HPA) axis with mental disorders, correlating in this context, the involvement of the CRHR1 and FKBP5 genes in inducing suicide behaviors." (PMID 40869374, 2025). "Characterisation of the Fkbp5 × ELA mouse model showed mechanistic and face validity with aspects of psychiatric disorders." (PMID 35449298, 2022). "FKBP5, a glucocorticoid receptor that can bind to immunosuppressive agents such as tacrolimus (FK506) and cyclosporin A, has emerged as a promising therapeutic target in the fields of cancer, psychiatric disorders, and metabolic diseases." (PMID 41271936, 2025). "FKBP5 is a well-known modulator of the negative feedback loop of the HPA axis and has been linked to a variety of stress-related psychiatric diseases." (PMID 37051166, 2023).
tumor (39 papers, 2011 to 2026). "A key FKBP5+ tumor subgroup was found to be closely associated with TME remodeling, which provides a possible method for assessing brain tumor staging." (PMID 37120690, 2023). "While the activity of FKBP51s Tregs appears to be effectively contrasted by anti-PD1, FKBP5 splicing in tumour-associated macrophages favours tumour tolerance and anti-PD1 resistance." (PMID 32317723, 2020). "In-depth resequencing identified 404 FKBP5 single nucleotide polymorphisms (SNPs) in normal and tumor DNA." (PMID 23936393, 2013). "Moreover, this explorative study suggests that manipulating FKBP5 splicing is a promising strategy for targeting tumour-associated macrophages and reprogramming these cells from immune suppressive to immune-activating and tumouricidal ones." (PMID 32317723, 2020). "Using these cell lines, we could perform a series of experiments based on FKBP5 rs73748206 genotypes, since this particular variant was found in both tumor and normal tissues." (PMID 23936393, 2013). "In addition, they had increased expression of the inhibitor interleukin 1 receptor antagonist (Il1rn) and of the FK506 Binding Protein 5 (Fkbp5); the latter was shown to play a key role in the immune suppressive activity of tumor associated suppressor granulocytes." (PMID 28620383, 2017). "Primary markers—FKBP5 and CLDN4 carry the headline: FKBP5 reports on the HP-engaged steroid/PPAR axis in adjacent tissue, while CLDN4 reports on tumor epithelial remodeling that underlies invasion." (PMID 41614938, 2026). "With the aim to gain more insights into the characteristics of the TME, we thought to analyze the transcript levels of FKBP5 alongside various genes related to proliferation and apoptosis in RNA extracted from tumor biopsies." (PMID 41256864, 2025). "PCNA, BCL2, TRAF2, XIAP and FKBP5 expression levels in whole RNAs extracted by 36 tumor tissue samples were quantified as relative expression, using expression from healthy donor PBMCs as a reference sample (=1)." (PMID 41256864, 2025). "When we transfected MCF-7 and FaDu cells with WT-ALOX12 and WT-FKBP5 genes, the recreated overexpression of ALOX12 and FKBP5 led to the induction of cellular death, inhibition of cellular invasion abilities, and strong inhibition of xenograft tumor growth." (PMID 39766798, 2024). "In tumor cells, FKBP5 has been demonstrated to bind AKT, leading to the dephosphorylation of AKT at Ser473 without affecting the phosphorylation site at Thr308." (PMID 39020442, 2024). "Because our results indicated that both ALOX12 and FKBP5 gene expression induced cellular death and inhibited the tumor growth and invasion ability of cancer cells, we aimed to examine the molecular mechanism of these antitumor effects." (PMID 39766798, 2024). "At the same time, our examination of tumor cells revealed that the spliced isoform of the FKBP5 gene can also serve as a prognostic marker for GBM." (PMID 38651817, 2024). "Our study not only re-emphasizes the importance of breaking down this barrier environment but also identifies the mechanisms and key cell subsets, such as the FKBP5+ tumor subgroup, that contribute to the barrier effect." (PMID 37120690, 2023). "With its splicing isoform, the FKBP5 gene addresses the tumor requirement to evade the immune system and survive immune attacks." (PMID 37415743, 2023). "A key FKBP5+ tumor subgroup was found to be responsible for pushing tumors into the barrier environment, which provides a possible way to evaluate the stage of PCNSL." (PMID 37120690, 2023). "Probably, the relationship between FKBP5 and tumor progression and aggressiveness, is represented by its implication in NF-kB and AKT signaling pathways, with key roles in tumorigenesis and response to antineoplastic chemotherapy." (PMID 33233407, 2020).